CRP (C-reactive protein)
Diseases named in the same sentence as CRP in open-access papers (continued):
Sharing a sentence is not in itself a finding about the gene and the disease.
interstitial lung disease (continued). "The diagnostic potential of serum KYN, QUNA, and TRP levels and the KYN/TRP ratio for DILD was analyzed using the AUROC values and compared with those of conventional serum markers for interstitial lung diseases (ILD) (KL-6 and SP-D) and inflammation (C-reactive protein [CRP])." (PMID 38221627, 2024). "Plasma Hsp90 demonstrated slightly superior ability to discriminate IIM patients from healthy controls, as well as IIM patients with interstitial lung disease or cardiac involvement from those without these manifestations, when compared to traditional soluble biomarkers such as CRP and CK." (PMID 35154129, 2022). "Notably, Hsp90 plasma levels were slightly superior to traditional biomarkers, such as C-reactive protein and creatine kinase, in differentiating IIM from HC, and IIM patients with cardiac involvement and interstitial lung disease from those without these manifestations." (PMID 35154129, 2022).
metastatic disease (48 papers, 2006 to 2025). "ECOG performance status 1, shorter interval from time of metastatic disease to inclusion, and increased baseline level of C‐reactive protein (CRP) were associated with CTC positivity in HR+ patients for both cutoffs." (PMID 38978352, 2025). "In the adjusted model, age, metastatic disease at time of intervention, bilateral hydronephrosis, low haemoglobin, high potassium, high white cell count, and high CRP level were associated with worse OS." (PMID 38406883, 2024). "Stepwise regression identified that a model including age, CRP, haemoglobin, creatinine, potassium, sodium, cancer type, metastatic disease, and bilateral hydronephrosis was associated with the lowest information loss in determining OS in the discovery cohort." (PMID 38406883, 2024). "Univariate Kaplan-Meier analyses of laboratory biomarkers and clinical parameters showed that CRP and metastatic disease at presentation were poor prognostic factors associated with overall survival and disease recurrence at 5 years (p < 0.05)." (PMID 36900365, 2023). "We reported that pathological CRP and metastatic disease were both associated with overall survival and recurrence-free survival." (PMID 36900365, 2023). "A multivariate Cox regression model showed that pathological CRP (≥1.0 mg/dL) [HR of 3.67; 95% CI, 1.46 to 10.42] and metastatic disease [HR of 4.27; 95% CI, 1.58 to 11.47] were associated with a higher risk of death at 5 years (p < 0.05)." (PMID 36900365, 2023). "Cluster B was associated with the frailest patients with metastatic disease, mainly driven by a high CRP level at baseline, and low albumin during the study follow-up." (PMID 34830936, 2021). "Recently, high levels of serum CRP have been associated with metastatic disease and a poor prognosis in various malignant cancers, including perihilar cholangiocarcinoma." (PMID 27733196, 2016). "This study confirms that a high preoperative CRP-level is significantly associated with muscle invasive and metastatic disease and that CRP can serve as an independent predictor of CSS." (PMID 23497335, 2013). "A high preoperative serum CRP level is associated with locally advanced and metastatic disease in patients with UUT-UC." (PMID 23497335, 2013). "In addition, pathological CRP, metastatic disease, radiotherapy and NLR were associated with recurrence-free survival at 5 years." (PMID 36900365, 2023). "A multivariate Cox regression model of negative prognostic factors was performed: pathological CRP (≥1.0 mg/dL) [HR of 2.66; 95% CI, 1.23 to 6.01] and metastatic disease [HR of 2.56; 95% CI, 1.13 to 5.55] were associated with a higher risk of disease recurrence at 5 years (p < 0.05)." (PMID 36900365, 2023). "In addition, pathological CRP (≥1.0 mg/dL) [HR of 2.66; 95% CI, 1.23 to 6.01] and metastatic disease [HR of 2.56; 95% CI, 1.13 to 5.55] were associated with a higher risk of disease recurrence at 5 years (p < 0.05)." (PMID 36900365, 2023). "However, we confirm these data by showing that pathologic CRP and metastatic disease are associated with overall survival in patients with Ewing’s sarcoma of not only the spine but also of the long bones." (PMID 36900365, 2023). "Pathological CRP and metastatic disease remained significant in the multivariate Cox analysis for both overall survival and recurrence-free survival." (PMID 36900365, 2023). "Univariate Kaplan-Meier analyses of laboratory biomarkers and clinical parameters showed that CRP, metastatic disease at presentation, and radiotherapy were poor prognostic factors associated with overall survival at 5 years (p < 0.05)." (PMID 36900365, 2023). "As in our study, the inflammation was defined as the presence of metastatic disease and the correlation with serum CRP was performed." (PMID 35276861, 2022). "CRP is a well-known acute-phase reactant that is significantly elevated in oncological patients with poor prognosis or metastatic disease." (PMID 33763243, 2020).
metastatic disease (continued). "To conclude, we found highest pretreatment CRP serum concentrations in patients with metastatic tumors and TCs." (PMID 28514756, 2017). "Patients with metastatic disease had significantly higher CRP (p = 0.047, γ = 0.338) and hepcidin (p = 0.036, γ = 0.356) level." (PMID 26517509, 2015). "In this study of 739 Finnish patients with PC and 760 healthy men, we evaluated the associations of CRP genotypes and haplotypes with total PC risk and PC progression, using prostate-specific antigen (PSA) as a marker of metastatic disease." (PMID 19436291, 2009). "In summary, it was thought that hemoglobin and ESR levels measured preoperatively in patients with solitary brain tumor (either glioblastoma or metastatic tumor) may be direct prognostic biomarkers, and CRP levels may be indirect prognostic biomarkers." (PMID 33584142, 2021). "Besides this, it was thought that this elevated level of serum CRP in patient with metastatic tumor itself." (PMID 33584142, 2021). "The prevalence of deficits on index items ranged from 6% (metastatic disease) to 73% (CRP > 5)." (PMID 29099916, 2018). "Additionally, C-reactive protein (CRP) was found to be elevated 41.1 fold in the serum of patients with metastatic disease compared to patients with BPH." (PMID 22355332, 2012). "Thus, it was thought that CRP level might be an indirect prognostic biomarker predicting the short-term prognosis in patients with solitary brain tumor (either glioblastoma or metastatic tumor)." (PMID 33584142, 2021). "As CRP is known as an acute-phase-protein in inflammation and many types of cancer develop in a chronic-inflammatory microenvironment, it may appear possible that infection directs the processes of tumor growth, recurrence, and metastatic disease." (PMID 27091202, 2016). "A higher serum CRP level was associated with poorly differentiated RCC (grade 1, 0.10 ± 0.01; grade 2, 1.32 ± 2.33; grade 3, 2.56 ± 2.59, P = 0.0036), local invasion (pT1–2, 0.43 ± 0.90; pT3–4, 2.52 ± 2.86, P = 0.0014), and metastatic disease (M1, 3.45 ± 3.15; M0, 0.52 ± 0.92, P = 0.0004)." (PMID 19656379, 2009). "In addition, it was concluded that ESR, CRP, blood hemoglobin levels and duration of stay in hospital could be biomarkers in predicting the short-term prognosis of patients with solitary brain tumor (either glioblastoma or metastatic tumor)." (PMID 33584142, 2021). "In the group of patients with metastatic disease at presentation, patients with pathological CRP had a poorer 5-year overall survival than patients with normal CRP (p = 0.010)." (PMID 36900365, 2023). "In all, 72 (75%) patients had not received cytotoxic chemotherapy for metastatic disease prior to the measurement of C-reactive protein and albumin concentrations." (PMID 16404432, 2006). "Six binary (sex, lung, lymph node, liver, bone, brain/CNS metastases) and eight continuous (age, time from diagnosis to metastatic disease, number of metastatic sites, ESR, C-reactive protein (CRP), haemoglobin, neutrophils, LDH) predictors were included in univariate FP analysis." (PMID 16736003, 2006). "The majority of enrolled patients had unfavorable prognostic baseline characteristics and had received multiple lines of previous systemic cancer therapy (including CPI), had multiple sites of metastatic disease, had elevated C-reactive protein and had tumors with negative or low PD-L1 scores." (PMID 39762422, 2025). "Systemic inflammation was highly prevalent in PreMiO patients with non-metastatic disease, as well as for those with metastatic disease; based on CRP measures for 56% of study patients, inflammation by cancer site ranged from 21% to 100% of M0 patients and 55% to 91% in M1 patients." (PMID 29108370, 2017). "Moreover, tumor cells have also been found to express CRP and SAA, which may explain the higher correlation between SAA and CRP in metastatic tumors than in non-metastatic tumors." (PMID 25884401, 2015).
metastatic disease (continued). "Our findings suggest that CRP and NLR are not negative prognostic factors and that metastatic disease, poor chemotherapy-induced tumor necrosis, and pathological AP correlate with poor overall survival in children with osteosarcoma of the extremities." (PMID 37504371, 2023). "Second, CRP and NLR are non-specific markers of inflammation and angiogenesis, and further studies are required to identify the key regulators controlling the systemic responses to metastatic disease." (PMID 28859644, 2017).
myositis (48 papers, 2012 to 2025). "Our anti-TIF1γ+ myositis patients in cluster 2 with the highest risk of cancer were more often males, had higher CRP levels, and more frequent shawl sign and V-neck sign." (PMID 35237262, 2022). "The low median CRP concentration we found in patients with influenza B is in accordance with findings in a recent study of influenza B-associated myositis in children." (PMID 33174788, 2020). "Cluster #6, with poor treatment responses to triple-combo therapy, was characterized by older age at disease onset, increased levels of CRP and KL-6, and hypoxia at diagnosis, which were reported as poor prognostic factors in patients with myositis-associated ILD." (PMID 35615085, 2022). "Importantly, we found that serum resistin levels were strongly associated with CRP and global disease activity, and a trend was also observed towards correlation between resistin levels and myoglobin in patients with myositis-specific anti-Jo-1 antibody in contrast to anti-Jo-1 negative patients." (PMID 22577940, 2012). "Investigations revealed neutrophil leukocytosis, high erythrocyte sedimentation rate (ESR) and C-reactive protein (CRP) levels whilst ultrasonography showed focal myositis of right quadriceps." (PMID 35705895, 2022). "The patient’s spiking fever and myositis resolved and CRP levels decreased to a normal level, corresponding with the dose escalation." (PMID 36211342, 2022). "This subpopulation was characterized by a proinflammatory phenotype, including an elevation of serum CRP and higher frequencies of pleuritis and myositis, which is consistent with previous reports." (PMID 36319843, 2022). "This study confirmed many single clinical and laboratory prognostic factors previously reported, such as periungual erythema, fever, and CRP, as risk factors for RP-ILD in myositis." (PMID 34646845, 2021). "In a large multicenter myositis-associated ILD cohort, CRP > 10 mg/L was revealed as an independent poor prognostic risk factor." (PMID 33516242, 2021). "PMN elastase level and ENR were positively correlated with myositis disease activity assessment, CK, lactate dehydrogenase, aspartate aminotransferase, alanine aminotransferase, C-reactive protein, and erythrocyte sedimentation rate." (PMID 31842908, 2019). "Muscle enzymes that may indicate DM disease activity, increased CRP and the presence of MSAs and myositis-related antibodies are also tests that can provide information about the disease prognosis." (PMID 38809450, 2024). "Since common infectious diseases have been excluded and CLL is not usually associated with elevated CRP, it most likely reflects myositis." (PMID 38991371, 2024). "In our patient cohort, cfDNA levels were associated with patient outcome as measured by the WHO clinical progression scale, mortality, complications such as myositis, elevated D-dimer and CRP levels, thus reflecting outcome, organ complications and inflammation." (PMID 37744227, 2023). "Therefore, SLE patients with high serum levels of the MPO-DNA complex were characterized by a higher frequency of myositis and pleurisy, higher serum level of CRP, and lower titers of anti-dsDNA antibodies." (PMID 36319843, 2022). "However, correlations between serum levels of CRP and lung function tests among anti-Jo-1-positive myositis patients with ILD have been reported, and elevated CRP levels have been described as a risk factor for developing ILD in patients with myositis." (PMID 30053824, 2018). "Aldolase, C-reactive protein (CRP), erythrocyte sedimentation rate (ESR), and Parvovirus B19 serum IgM were elevated, but creatine kinase, extended myositis antibody panel, and 3-hydroxy-3-methylglutaryl coenzyme A (HMG CoA) reductase antibody were normal." (PMID 40486395, 2025). "Check myositis‐specific autoantibodies (anti‐MDA5, anti‐TIF1‐γ, and anti‐NXP2), inflammatory markers (ESR, CRP, and ferritin), imaging, endoscopy, and tumor markers." (PMID 40012936, 2025).
myositis (continued). "All patients underwent laboratory analysis for C-reactive protein, liver enzymes (AST and ALT) and muscle enzymes (creatine kinase), blood count, and myositis autoantibodies." (PMID 36330424, 2022). "Decision tree can conveniently stratify and manage anti-TIF1γ+ myositis patients with disease duration, NLR, and CRP in clinical practice." (PMID 35237262, 2022). "Blood test revealed an elevated C-reactive protein (CRP) level (19.3 mg/dL) and white blood cell (WBC) count (15,100 cells/μL), with normal levels of creatinine kinase and myositis-related antibodies (antinuclear antibody, Jo-1, MDA5, Mi-2, TIF1g, RNA polymerase, and Scl-70)." (PMID 35284230, 2022). "In addition, serum MMP-9 levels were positively correlated with WBCs, neutrophils, CK, CRP, ESR, and LDH in myositis patients." (PMID 31440381, 2019). "This included serum antinuclear antibodies (ANA), a myositis expanded antibody panel, lactate dehydrogenase (LDH) isoenzymes, aldolase, acetylcholine receptor antibody panel, anti-MuSK antibody test, erythrocyte sedimentation rate (ESR), and C-reactive protein (CRP)." (PMID 39897188, 2025). "Whether the elevated CRP reflects infectious disease, CLL, or simply myositis remains speculative." (PMID 38991371, 2024). "C-reactive protein (CRP) is currently not used as a biomarker of disease activity in myositis." (PMID 30053824, 2018). "Although CRP is not considered to be a marker of disease activity in most systemic diseases, some studies indicates its role mainly in patients with lung involvement, including myositis." (PMID 30053824, 2018). "Biochemical findings included elevated hs-TnT (470 ng/L, normal < 10), elevated C-reactive protein (CRP) (94 mg/L, normal < 10), and a positive antinuclear antibody (ANA) testing (1:160, granular pattern), with negative extractable nuclear antigen (ENA), myositis, and scleroderma panels." (PMID 40433220, 2025).
ulcer (48 papers, 2013 to 2026). "MMP-9 and CRP showed strong correlations with ulcer severity, highlighting their diagnostic utility for early screening." (PMID 40364880, 2025). "Recent research on DFIs highlights risk factors such as previous hospitalization, ulcer size, surgical therapy, and C-reactive protein." (PMID 39165660, 2024). "Our results also suggest that the presence of these ulcers is associated with a more active disease, including higher CRP and fecal calprotectin levels, greater bowel wall thickening, and longer length of disease, on average." (PMID 39292244, 2024). "Our study revealed a significant increase in IL-6, TNF-α, and CRP levels in ulcer patients compared to the pre-ulcer and control groups." (PMID 40364880, 2025). "A strong positive correlation between HbA1c and CRP (r = 0.72, p < 0.001) reinforces the concept that poor metabolic control drives systemic inflammation, which in turn worsens ulcer-healing trajectories." (PMID 41367458, 2025). "The results indicated a strong positive correlation between inflammatory biomarkers (IL-6, TNF-α, CRP) and HbA1c and ulcer severity, suggesting that increased systemic inflammation is associated with poor glycemic control and worsening ulcer conditions." (PMID 40364880, 2025). "Model 1 enables initial risk assessment using simple clinical parameters (e.g., previous antibiotic use, surgical history, and ulcer size), whereas Model 2 enhances predictive precision with the integration of CRP (AUC increased from 0.763 to 0.789)." (PMID 41458536, 2025). "In the present study, a progressive increase in the levels of IL-6, TNF-α, and CRP was observed across the control, pre-ulcer, and ulcer groups, indicating that inflammation plays a critical role in the early pathogenesis of DFUs." (PMID 40364880, 2025). "Demographic data, ulcer classification, fasting and postprandial blood glucose, glycated hemoglobin (HbA1c), and CRP levels were recorded and analyzed to determine their correlation with wound healing and clinical outcomes." (PMID 41367458, 2025). "The analysis results demonstrated that previous antibiotic therapy, surgical therapy, ulcer size>4cm2, and CRP are independent influencing factors for the occurrence of MDRO infection in DFU patients." (PMID 41458536, 2025). "Data were collected on demographics, ulcer severity (Wagner Grade), glycemic status (HbA1c), biochemical markers (C-reactive protein [CRP], interleukin-6 [IL-6], tumor necrosis factor-alpha [TNF-α], and serum albumin), and clinical outcomes." (PMID 40821188, 2025). "Patients in the intervention group experienced significantly greater reductions in ulcer area and re-epithelialization, accompanied by improvements in systemic biomarkers, including glycemia, HbA1c, CRP, and fibrinogen." (PMID 41155052, 2025). "DFU induces marked upregulation of inflammatory markers such as TNF-α, IL-6 and CRP, which correlate with ulcer severity." (PMID 39508881, 2025). "A similar trend was observed for TNF-α (ulcer: 12.1 ± 3.0 pg/mL, pre-ulcer: 6.9 ± 1.5 pg/mL, control: 3.5 ± 0.7 pg/mL) and CRP (ulcer: 7.8 ± 1.6 mg/L, pre-ulcer: 3.4 ± 0.7 mg/L, control: 1.2 ± 0.3 mg/L)." (PMID 40364880, 2025). "Serum levels of IL-6, TNF-α, and CRP showed a progressive increase from the control group to the ulcer group, with statistically significant differences (p < 0.001)." (PMID 40364880, 2025). "It was reported that there was a statistically significant improvement in ulcer size, blood sugar regulation, C‐reactive protein (CRP) level and plasma antioxidant capacity in the patient group receiving magnesium supplementation." (PMID 39319424, 2024). "Patients with active inflammation seen on endoscopic evaluation, including ulcer or non-ulcer inflammation, had a median baseline CRP level of 30.1 mg/L, while those with normal endoscopic findings had a baseline CRP level of 15.4 mg/L (p=0.016)." (PMID 37476185, 2023).